RNU6-818P (RNA, U6 small nuclear 818, pseudogene)
Gene: Small nuclear RNA gene on chromosome 4 (88,201,703 to 88,201,810, forward strand). Ensembl gene ENSG00000201707.
Homologues: Orthologues: chimpanzee U6 (99% identical), macaque U6 (93% identical), pig U6 (75% identical), guinea pig U6 (71% identical), rabbit U6 (67% identical). Paralogues in human: RNU6-16P (85% identical), RNU6-11P (84% identical), RNU6-144P (84% identical), RNU6-235P (84% identical), RNU6-28P (84% identical), RNU6-333P (84% identical), RNU6-37P (84% identical), RNU6-639P (84% identical), RNU6-774P (84% identical), RNU6-86P (84% identical), RNU6-87P (84% identical), RNU6-21P (83% identical), and 1287 more.